AGFG2 (ArfGAP with FG repeats 2)
Synonyms: HRBL; RABR
Tractability: PROTAC: ubiquitination databases record sites on it.
Gene: Protein-coding gene on chromosome 7 (100,539,190 to 100,568,220, forward strand). Ensembl gene ENSG00000106351.
Subcellular location (Human Protein Atlas): Cytosol
Gene Ontology:
Molecular function: GTPase activator activity
Biological process: acrosome assembly; intermediate filament organization; spermatid nucleus differentiation
Cellular component: membrane; cytoplasm; cytoplasmic vesicle
Genetic constraint (gnomAD): Loss-of-function variants: 28 observed, 43.96 expected, observed/expected ratio (o/e) 0.64, 90% interval 0.47 to 0.87. The upper end of that interval is the gene's LOEUF score, 0.87, which puts it in group 3 of 6, group 1 being the genes least tolerant of losing a copy. Missense variants: 596 observed, 597.85 expected, observed/expected ratio (o/e) 1, 90% interval 0.93 to 1.07. Synonymous variants: 228 observed, 242.44 expected, observed/expected ratio (o/e) 0.94, 90% interval 0.84 to 1.05.
Homologues: Orthologues: chimpanzee AGFG2 (99% identical), macaque AGFG2 (96% identical), pig AGFG2 (87% identical), rabbit AGFG2 (86% identical), guinea pig AGFG2 (85% identical), mouse Agfg2 (82% identical), rat Agfg2 (78% identical), dog AGFG2 (68% identical), zebrafish agfg2 (33% identical). Paralogues in human: AGFG1 (46% identical), SMAP1 (16% identical), ARAP2 (15% identical), ARAP3 (14% identical), ARAP1 (14% identical), ADAP1 (14% identical), ASAP1 (14% identical), ASAP2 (14% identical), SMAP2 (11% identical), ARFGAP2 (11% identical), ASAP3 (11% identical), ADAP2 (11% identical), and 16 more.
Diseases named in the same sentence as AGFG2 in open-access papers:
AGFG2 is named in the same sentence as 12 diseases in open-access papers, as found by Europe PMC text mining. Sharing a sentence is not in itself a finding about the gene and the disease. The quoted sentences say what the papers report.
Alzheimer disease (1 paper, 2024). A progressive, neurodegenerative disease characterized by loss of function and death of nerve cells in several areas of the brain leading to loss of cognitive function such as memory and language. "Many of these genes have been previously linked to brain-related disorders, including Alzheimer’s disease (WDR12, AGFG2, and CDK5RAP3), schizophrenia (SRA1, WDR55, CORO7, DDAH2, PCDHA8), autism spectrum disorder (MAPK3, PCDHA13), and major depressive disorder (ZMAT2 and ITIH4)." (PMID 39269986, 2024).
Stroke (1 paper, 2023). Sudden impairment of blood flow to a part of the brain due to occlusion or rupture of an artery to the brain. "Six proteins (AGFG2, C1QTNF1, CHIT1, DNAJC15, FTL, and OLR1) have been reported to be implicated in other neurodegenerative diseases such as AD, ALS, or stroke, but not in PD." (PMID 37422510, 2023).
tumour (1 paper, 2015). "The second subcategory contains a reciprocal relationship between normal oesophagous and OAC where expression is reduced in the tumour samples, and hence shows an anti-correlation with FOXM1 expression, despite representing direct targets (eg AGFG2 and CCDC85C)." (PMID 25889361, 2015).
AGFG2 also shares sentences with these, for which no sentence is quoted: autism spectrum disorder (1 paper); breast carcinoma (1); cancer (1); colorectal cancer (1); diabetes (1); major depressive disorder (1); neurodegenerative disease (1); schizophrenia (1); type 2 diabetes (1).